IFNG (interferon gamma)
Diseases named in the same sentence as IFNG in open-access papers (continued):
Sharing a sentence is not in itself a finding about the gene and the disease.
tumor (continued). "Overall, these findings imply that FAK deletion reprogrammes the response of PDAC cells to IFNγ, resulting in increased expression of pathways important for T-cell tumour recognition." (PMID 36977556, 2023). "Intra-tumoral inflammation and, notably, IFNγ secretion are known to impair the anti-tumoral activity of cytotoxic lymphocytes (CTL) by promoting tumor immune escape through the induction of ICP over-expression, which causes immune cell exhaustion and anergy." (PMID 37296927, 2023). "To assess this, in the first instance, we investigated gene expression differences in tumours from IFNγ-naïve and chronic IFNγ-treated YUMM2.1 cells (treated with IgG2a control antibodies) by undertaking RNA-seq and GSEA." (PMID 37752135, 2023). "Anti-tumor immune cells are known to produce an array of cytokines such as TNFα, IFNγ, and CD107 as a measure of their activity." (PMID 36900259, 2023). "Meanwhile, the IFNγ secreted by activated T cells leads to an increase in GSDMB as well as PD‐L1 expression on tumor cells." (PMID 37587833, 2023). "In murine models, TIGIT+ NK cells recovered from either spleen or tumors of tumor-bearing mice had a lower frequency of IFNγ-, TNFα-, or DNAM-expressing cells as compared to TIGIT− NK cells." (PMID 37345049, 2023). "This is because BRAF inhibitors are supposed to modulate the tumor immune microenvironment by increasing interferon-gamma production on intratumoral CD4+ T lymphocytes and increasing CD8+ TILs." (PMID 37569757, 2023). "ATP-stimulated dendritic cells produce IL-1 and IL-18, which synergize with IFNγ in the induction of tumor-specific CD8 T cells." (PMID 36831435, 2023). "IFNγ and TNFα production triggered in NK cells against these tumor cells was significantly lower than that induced by TriKE in response to NCI-H460, for all disease stages (I-IVB) and timepoints (before treatment, after treatment or at progression)." (PMID 36911670, 2023). "Activated T cells in the tumor microenvironment release IFNγ and activate the JAK1/2-STAT1/3 pathway through IFNγ receptors (IFNγR1/2) on cancer cells." (PMID 37190239, 2023). "The anti-tumor activity of IFNγ is manifested by the activation of antigen-presenting cells, the arrest of the cell cycle in the G1 phase, the stimulation of cell ischemia and apoptosis." (PMID 37509655, 2023). "IFNγ directly favors tumor growth control by enhancing the immunogenicity of tumor cells, induces IP-10 secretion facilitating (CXCR3+) immune cell infiltration, and can prime macrophages to an M1-like phenotype inducing proinflammatory cytokine release." (PMID 36839699, 2023). "Flow cytometry analysis showed the increase in IFNγ- and granzyme B (Gzmb)-secreting tumor-infiltrating T cells by TAS-115 treatment." (PMID 37258621, 2023). "Altogether, we provide evidence that IFNγ signaling in CD8 T cells inhibits anti-tumor responses by limiting T cell expansion and infiltration." (PMID 36658158, 2023). "Our models predicted only a minor contribution of CTL killing toward tumor control compared to the IFNG-mediated cell-cycle arrest, consistent with our prior findings." (PMID 37182110, 2023). "NK cells also produce pro-inflammatory cytokines such as IFNγ and TNFα to promote anti-tumor activity of other immune cells or to directly inhibit tumor cells." (PMID 37277776, 2023). "Th1 cells are characterized by the production of IL-2 and IFNγ, which suppresses tumor progression at least by supporting CD8+ T cell function, facilitating recruitment of antigen-presenting cells, and inhibiting tumor angiogenesis." (PMID 37620312, 2023). "On the other hand, lymphocytes play a crucial role in controlling tumor growth by secreting cytokines such as interferon-gamma and TNF-α, which results in a good prognosis." (PMID 37894429, 2023). "Inflammatory cytokines such as tumor necrosis factor-related apoptosis-inducing ligand (TRAIL), interferon-gamma (IFNγ), and interleukin-12 (IL-12) have been reported to demonstrate anti-tumor immunity." (PMID 37893013, 2023).
tumor (continued). "We further performed an ex vivo IFNγ ELISPOT assay using splenic T cells to validate the generation of tumor specific T cells." (PMID 37296221, 2023). "PD-L1, an extensively investigated molecule involved in tumor immune, is exclusively regulated by IFNγ according to traditional research." (PMID 38933287, 2023). "Our work puts IFNγ at the center of continuous T cell dysfunction and reinforces the importance to uncouple different outcomes triggered by IFNγ to specifically leverage IFNγ-driven anti-tumor immunity." (PMID 36658158, 2023). "Higher levels of effector cytokines IFNγ and TNFα and tumor‐infiltrated CD45+ immune cells after 8FNs vaccination indicated that 8FNs better rejuvenated the immunosuppressed microenvironment compared to aluminum salts‐adjuvanted vaccines." (PMID 37162249, 2023). "The proinflammatory subtype of macrophages (M1) are producers of the cytokines IL-1β and IFNγ; however, further phenotyping of cell surface markers would be required to determine if the macrophages in the treated tumor populations were of an M1 phenotype." (PMID 37893110, 2023). "As shown, the Setd2KO tumor burden on the pancreas was reduced in both a‐Ly6G and a‐PD‐1 treatment groups in Setd2WT and Setd2KO tumor‐bearing mice, accompanied by a marked increase in IFNγ production in CD8+ T cells." (PMID 36453584, 2023). "Selected genes are reflecting main anti-tumor immune pathways, such as Th1 signaling (IFNG, TBX21, CD8A/B, IL12B, STAT1 and IRF1), Th1 chemoattraction (CXCL9, CXCL10 and CCL5) and cytotoxic functions (GNLY, PRF1, GZMA, GZMB and GZMH)." (PMID 37726776, 2023). "The increased expression of Stat1, Ido1, and H2ab1 suggested that the IFNγ signal in the tumor was upregulated and accompanied by elevated IFNγ expression in CTLs." (PMID 36793737, 2023). "Consistently with the M1 activation pattern demonstrated for the VSSP-BMDMs, the frequency of tumor-infiltrating CD8+ T cells secreting IFNγ and Granzyme B were increased in the TME, suggesting an immunostimulatory potential of VSSP-BMDMs." (PMID 37055829, 2023). "Subsequently, it was found that elevated secretion of IFNγ by NK cells enhanced the level of FN1 in the tumor, resulting in architectural alteration and less aggressive metastasis." (PMID 37190251, 2023). "The three genes (CALR, IFNB1, and IFNG) were involved in anti-tumor immunity, which improved the predictive performance of this signature." (PMID 38023241, 2023). "Of significance, the expression of coinhibitory receptors (PD1, KLRG1, LAG3, and TIM3) was considerably lower in CD8+ T cells retrieved from B16 Mgst1 KD tumor, and there was an increase in cytokine response (IFNγ and TNFα) along with Granzyme B." (PMID 37321450, 2023). "The number of activated CD8+IFNγ+ T cells in tumor‐infiltrating lymphocytes in the xenograft after L‐CTB‐hsCD80 treatment increased significantly, whereas the number of activated T cells modestly increased after L‐hsCD80 treatment, supporting our inference." (PMID 37476068, 2023). "While treatment of both tumor types induced immune infiltration and IFNγ, we found a defining feature of resistance was elevation of immunosuppressive cytokines like TGFβ, which blunted IFNγ signaling, especially in regulatory T cells." (PMID 37552475, 2023). "Multiplex spatial imaging revealed clusters of high NOS2 expressing cells proximal to areas of stroma-restricted CD8+ T cells that are known to produce IFNγ and suggest a small inflammatory niche at the tumor/stroma interface in these tumors." (PMID 37169743, 2023). "We anticipate that this approach also likely influences tumor vasculature through IFNγ signaling to further promote anti-tumor responses." (PMID 37550294, 2023). "SNX9 knockout enhances memory differentiation and IFNγ secretion of adoptively transferred T cells and results in improved anti-tumor efficacy of human chimeric antigen receptor T cells in vivo." (PMID 36732507, 2023).
tumor (continued). "In accordance with Raji tumor activating tumor-specific T-cell responses, isolated splenic T cells from Raji-challenged mice with regressing tumors exhibited Raji-specific reactivity in an IFNγ ELISpot assay." (PMID 37087494, 2023). "Using syngeneic mouse tumour models, we confirm that chronic IFNγ exposure confers resistance to immunotherapy targeting PD-1 (α-PD-1) in immunocompetent female mice." (PMID 37752135, 2023). "Purified splenic T cells from Raji-experienced mouse showing Raji tumor control and Ramos rejection demonstrate IFNγ ELISpot response to both Raji and Ramos tumor." (PMID 37087494, 2023). "A unique aspect of NHS-IL12 versus rIL-12 is its ability to localize to the tumor, thereby eliciting local IFNγ production via activation, maturation, and expansion of NK and CD8+ TILs." (PMID 38260854, 2023). "Alongside changes in target expression, significant increases in serum IFNγ levels and T-cell activation/function in tumor-draining lymph nodes were observed following treatment with the mIgG1 anti-ICOS mAb and the anti-PD-1 mAb combined." (PMID 37593752, 2023). "When anti-IFNγ antibodies were administered simultaneously with cisplatin, tumour volume was observed to be similar to that in the control group." (PMID 37056922, 2023). "Macrophages intaking glucose can develop into M1-type macrophages after receiving interferon gamma (IFN-γ) secreted by Th1 cells, and the anti-tumour ability of M1-macrophages can be enhanced." (PMID 37108242, 2023). "In this study, results revealed that IFNγ stimulation induced the endocytosis of VE-cadherin, neutralised IFNγ reversed cisplatin-induced vascular damage, improved the expression of VE-cadherin on tumour blood vessels, and promoted tumour vascular functions." (PMID 37056922, 2023). "Treatment of U-87, U-138, and GBM neurosphere cell lines has shown elimination of tumor cells in vitro, with induction of interferon gamma and IL-2 production." (PMID 36900205, 2023). "As for IFNG, in the background of malignant tumors, IFNG has been regarded as a central player in anti-tumor immunity." (PMID 37520534, 2023). "Recent studies in different murine tumor models demonstrated that the long-distance IFNγ effects critically contribute to tumor control, and that control is lost when tumor cells acquire resistance to IFNγ, as we observed also in the clinical setting." (PMID 37965314, 2023). "It is possible that IFNγ mainly inhibits hyperproliferative sprouting vasculatures in blocking immune checkpoint, while IFNγ stimulates glycolytic endothelial cells to accelerate the disruption of vascular integrity in tumours with chemotherapy." (PMID 37056922, 2023). "IFNγ is a cytokine with antitumor activities, involved in the control of tumor initiation and progression." (PMID 37022566, 2023). "RNA-seq and GSEA indicated that the TME in tumours derived from YUMM2.1 that spontaneously progressed after α-PD-1 therapy was characterised by upregulated IFNγ-signalling and was T cell inflamed in contrast to the tumours derived from IFNγ pre-treated cells." (PMID 37752135, 2023). "IFNγ is a well-known cytokine with anti-tumor immune effects, including activation and proliferation of tumor-infiltrating lymphocytes." (PMID 38026978, 2023). "GM-CT-01 enhances the infiltration of T cells into the tumor microenvironment and induces IFNγ synthesis." (PMID 36873388, 2023). "CD4+ T cell-derived IFNγ can either act on tumour cells or through IFN-dependent activation of iNOS-expressing tumouricidal myeloid cells." (PMID 37316667, 2023). "Here, we describe CAR T cells targeting tumor-associated glycoprotein-72 (TAG72), utilizing the CD28 transmembrane domain upstream of the 4-1BB co-stimulatory domain as a driver of potent anti-tumor activity and IFNγ secretion." (PMID 37550294, 2023).
tumor (continued). "γδ Tcells producing effector cytokines IFNγ kill tumor cells via perforin and granzyme, whereas γδ T cells expressing IL17 support tumor growth and metastasis by recruiting other immunosuppressive immune cells, such as MDSC." (PMID 37568713, 2023). "CAR T cell-mediated IFNγ production facilitated by IL-12 signaling is required for tumor cell killing, which is recapitulated by engineering an optimized membrane-bound IL-12 (mbIL12) molecule in CAR T cells." (PMID 37550294, 2023). "IL-12 further causes a substantial amount of IFNγ to be produced (a cytostatic/cytotoxic and anti-angiogenic agent), in addition, IL-12 can upregulate MHC I and II expression on tumor cells for improved antigen recognition and lysis." (PMID 36831131, 2023). "Gene set enrichment analysis (GSEA) of bulk RNA sequencing showed high stromal STAT3 tumours were characterised by enrichment of IFNγ, upregulation of KRAS signalling and inflammatory signalling Hallmark pathways." (PMID 37199043, 2023). "When treating multiple EphA2+ GBM cell lines with optimized CAR T cell design, treatment showed tumor cell lysis with significant upregulation of interferon gamma and IL-2, and only low levels of induced inhibitory cytokines IL-10 and IL-4." (PMID 36900205, 2023). "When anti-IFNγ antibody was administered two days after the first injection of cisplatin, it largely promoted tumour chemotherapy." (PMID 37056922, 2023). "Immunohistochemical analysis of tumor tissue revealed tenfold more colocalization of IFNγ–GFP voxels with HS voxels than colocalization of IFNγΔKRKR–GFP voxels with HS voxels within the CD146 volume." (PMID 36732425, 2023). "In conclusion, IFNγ blockade in capillary leak site protected tumour blood vessels from lactate-dependent VE-cadherin loss and enhanced drug delivery during chemotherapy, which provides a basis for tissue-specific IFNγ blockade for tumour therapy." (PMID 37056922, 2023). "IFNγ acts together with granzyme B and perforin to initiate apoptosis in tumor cells but also enables the synthesis of immune checkpoint inhibitory molecules, such as PD-L1, thus stimulating other immune-suppressive mechanisms." (PMID 38003396, 2023). "We further corroborated our findings using a recursive tumor cell killing assay, showing a requirement for IFNγ in sustained in vitro anti-tumor activity." (PMID 37550294, 2023). "Further, N803 plus vaccine expanded CD8+ T cells, producing IFNγ and/or TNFα in the tumor microenvironment and the periphery." (PMID 37371081, 2023). "For example, secretion of interferon gamma (IFN-γ) promotes the maturation of dendritic cells (DCs), stimulates helper T cell function, and increases the expression of MHC-I on tumor cells, thereby increasing their susceptibility to T cells." (PMID 37426654, 2023). "Poor immunogenicity in CRCpMMR is further supported by interferon gamma (IFN-γ) unresponsiveness of both tumor cells and TAMs." (PMID 37370706, 2023). "The IFNγ neutralising antibody was administered two days after the first cisplatin injection in the transplanted LLC tumour models." (PMID 37056922, 2023). "Although the PBMC and tumor cells were from different dogs, and thus the dog lymphocyte antigen (DLA) was not matched between the cPBMCs and K9TCC cells, the 12C chimeric antibody enhanced tumor cell killing activity and IFNγ secretion." (PMID 37377896, 2023). "Conversely, infiltration of tumor-fighting cytotoxic CD8+ T cells, Th1 cells and generation of mediators such as IFNγ in the TME have been shown to collaborate in mounting anti-tumor responses resulting in cancer regression." (PMID 38074634, 2023). "We also contrasted gene expression in tumours derived from chronic IFNγ stimulated YUMM2.1 cells treated with α-PD-1 monotherapy with α-PD-1 + PARP14i combination therapy treated by sequencing mRNA from bulk tumours." (PMID 37752135, 2023).
tumor (continued). "The sorted cells were co-cultured with C51 tumor cells that had been pre-treated with IFNγ to upregulate PD-L1; the CD8+ T cell phenotype was flow-cytometrically analyzed 3 days later." (PMID 37045833, 2023). "TIGIT blockade upregulated multiple gene sets related to NK cell anti-tumor responses, including inflammatory response-related genes, TNFα signaling via NFкB, and IFNγ response-related gene sets." (PMID 37345049, 2023). "Macrophages integrated within the MTS had a mixed M2/M1 phenotype, abrogated the anti-proliferative effect of trastuzumab on tumor cells, and responded to IFNγ with increased M1-like polarization." (PMID 37346794, 2023). "Although cisplatin treatment did not reduce the NG2+ pericyte coverage compared with control, anti-IFNγ increased NG2+ pericyte coverage compared with cisplatin-treated tumours." (PMID 37056922, 2023). "The subsequent consequences of pro-inflammatory IFNG signaling for tumor progression are multipart since diverse actions meet and must therefore be seen in the specific context of disorder." (PMID 37138100, 2023). "We showed that AC484 enhances the anti-tumour effects of IFNγ and has broad phenotypic and functional effects on several subsets of tumour-infiltrating immune cells, including macrophages, dendritic cells, T cells and NK cells." (PMID 37794185, 2023). "TSPO upregulation in the tumor cells required antigen specific activation of T cells interacting with the tumor cells and was initiated through IFNγ and TNFα secreted by activated T cells." (PMID 37158962, 2023). "Numerous studies have shown that IRF1, a transcription factor that mediates IFNγ signaling, promotes both PD-L1 upregulation in tumor cells and tumor progression in vivo." (PMID 37024504, 2023). "ROR1-based CAR-T cell therapy was also shown to induce MDA-MB-231 apoptosis in tumor models through significant IL-2 and IFNγ production." (PMID 36900394, 2023). "The first tested condition was the activation of cytokines involved in polarizing macrophages to a cytotoxic tumor-eliminating phenotype: IFNG, IFNB, TNFA, and IL1B." (PMID 37283734, 2023). "When ctDNA detection was combined with the level of tumour mutational burden (TMB) and a tumour-derived interferon signature (including HLA-DRA, CXCL9/10/11, GZMA, PRF1, CCR5, IFNG, IDO1 and STAT1), the predictive value of the combined score was enhanced." (PMID 38201222, 2023). "Peptide-expanded populations of TILs recognizing either ERBB2 or MOB1A epitopes from two patient samples (OV777 and OV870) responded to matched tumor cells with IFNγ production." (PMID 36943460, 2023). "Here, we examined a key nexus of IFNγ-mediated tumor cell fitness, metabolic reprogramming by upregulating the essential nicotinamide adenine dinucleotide (NAD+) salvage pathway enzyme, nicotinamide phosphoribosyltransferase (NAMPT)." (PMID 36900204, 2023). "Interferon-gamma (IFN-γ), a crucial cytokine, plays a pivotal role in initiating and maintaining potent anti-tumor reactions." (PMID 37627215, 2023). "In order to characterize the in vitro cytotoxic properties of the CAR T cells obtained more comprehensively, the IL2 and IFNg levels in the supernatants of CAR T cells co-incubated with tumor cells for 12 h at a 1:2 ratio were measured by ELISA." (PMID 36835110, 2023). "Recent studies have implied that CD8 T cells activated by immunotherapy can promote tumor cell lipid peroxidation and ferroptosis by releasing interferon-gamma (IFNγ), thereby enhancing the anti-tumor efficacy of immunotherapy." (PMID 36702843, 2023). "Their functions are similar to that of cytotoxic T cells, considering they induce anti-viral and anti-tumor immunity by producing IFNγ, granzyme B, and perforin, resulting in cell lysis." (PMID 37266839, 2023). "IL-10 is an anti-inflammatory cytokine that plays a crucial role in tumor killing and inhibits the production of IFNg, IL-2, IL-3, and TNFα." (PMID 37445686, 2023).